Y_RNA (Y RNA )
Gene: Miscellaneous RNA gene on chromosome 3 (66,003,839 to 66,003,940, reverse strand). Ensembl gene ENSG00000202071.
Homologues: Orthologues: chimpanzee Y_RNA (99% identical), guinea pig Y_RNA (86% identical). Paralogues in human: RNY3P1 (85% identical), Y_RNA (85% identical), Y_RNA (84% identical), Y_RNA (83% identical), RNY3 (82% identical), RNY3P11 (82% identical), Y_RNA (82% identical), RNY3P14 (81% identical), Y_RNA (81% identical), Y_RNA (80% identical), RNY3P4 (79% identical), Y_RNA (79% identical), and 93 more.